LINC00837 (long independently transcribed non-coding RNA 837)
Gene: Long non-coding RNA gene on chromosome 10 (28,789,188 to 28,796,126, reverse strand). Ensembl gene ENSG00000235824.
Diseases named in the same sentence as LINC00837 in open-access papers:
LINC00837 is named in the same sentence as 1 disease in open-access papers, as found by Europe PMC text mining. Sharing a sentence is not in itself a finding about the gene and the disease. The quoted sentences say what the papers report.
cancer (1 paper, 2023). A tumor composed of atypical neoplastic, often pleomorphic cells that invade other tissues. "However, up until now, it is still unkwon whether SNHG17 and LINC00837 involve in regulating cancer progression via affecting lipid metabolism, which makes investigations on this issue especially important and necessary." (PMID 37231440, 2023). "Furthermore, little is known of the biological functions of LINC00837, with a few studies showing the involvement of LINC00837 in the regulation of dendritic cell functions, while there is no information on its role in cancer." (PMID 37231440, 2023).